UPK1A (uroplakin 1A)
Description:
Component of the asymmetric unit membrane (AUM); a highly specialized biomembrane elaborated by terminally differentiated urothelial cells. May play an important role in normal bladder epithelial physiology, possibly in regulating membrane permeability of superficial umbrella cells or in stabilizing the apical membrane through AUM/cytoskeletal interactions (By similarity).
Synonyms: UP1a; UPIa; UPKa; TSPAN21
Tractability: Antibody: its Gene Ontology location is reachable by antibodies, with high confidence; UniProt predicts a signal peptide or a membrane-spanning region.
Gene: Protein-coding gene on chromosome 19 (35,666,517 to 35,678,481, forward strand). Ensembl gene ENSG00000105668.
Subcellular location: Membrane
Pathways (Reactome):
Disease: Attachment of bacteria to epithelial cells
Gene Ontology:
Molecular function: protein binding
Biological process: epithelial cell differentiation
Cellular component: cell surface; extracellular exosome; endoplasmic reticulum; membrane; plasma membrane; protein-containing complex; apical plasma membrane; apical plasma membrane urothelial plaque
Genetic constraint (gnomAD): Loss-of-function variants: 31 observed, 33.98 expected, observed/expected ratio (o/e) 0.91, 90% interval 0.69 to 1.23. The upper end of that interval is the gene's LOEUF score, 1.23, which puts it in group 5 of 6, group 1 being the genes least tolerant of losing a copy. Missense variants: 340 observed, 371.62 expected, observed/expected ratio (o/e) 0.91, 90% interval 0.84 to 1. Synonymous variants: 135 observed, 143.17 expected, observed/expected ratio (o/e) 0.94, 90% interval 0.82 to 1.09.
Homologues: Orthologues: mouse Upk1a (93% identical), guinea pig UPK1A (89% identical), rat Upk1a (88% identical), pig UPK1A (87% identical), dog UPK1A (86% identical), chimpanzee UPK1A (84% identical), macaque UPK1A (81% identical), rabbit UPK1A (74% identical), tropical clawed frog upk1a (60% identical), zebrafish upk1a (43% identical). Paralogues in human: UPK1B (38% identical), TSPAN14 (21% identical), TSPAN17 (20% identical), TSPAN5 (20% identical), TSPAN4 (20% identical), CD37 (19% identical), CD151 (19% identical), TSPAN11 (18% identical), TSPAN18 (18% identical), CD63 (18% identical), CD82 (18% identical), TSPAN1 (18% identical), and 20 more.